RNU6-1310P (RNA, U6 small nuclear 1310, pseudogene)
Gene: Small nuclear RNA gene on chromosome 1 (168,263,375 to 168,263,481, reverse strand). Ensembl gene ENSG00000206880.
Homologues: Orthologues: chimpanzee U6 (99% identical), macaque U6 (88% identical), guinea pig U6 (79% identical), rabbit U6 (78% identical), mouse Gm25294 (74% identical). Paralogues in human: RNU6-1083P (93% identical), RNU6-28P (89% identical), RNU6-86P (89% identical), RNU6-1311P (88% identical), RNU6-38P (88% identical), RNU6-560P (88% identical), RNU6-1124P (87% identical), RNU6-11P (87% identical), RNU6-1316P (87% identical), RNU6-24P (87% identical), RNU6-338P (87% identical), RNU6-37P (87% identical), and 1285 more.